INS (insulin)
Diseases named in the same sentence as INS in open-access papers (continued):
Sharing a sentence is not in itself a finding about the gene and the disease.
subarachnoid hemorrhage (4 papers, 2011 to 2020). A serious neurological disorder characterized by intracranial hemorrhage into the subarachnoid space. "This is in contradistinction to brain chemistry studies in subarachnoid haemorrhage indicating that insulin administration per se decreases cerebral glucose independently of systemic glycaemia." (PMID 29368635, 2018). "• Further study is needed to understand how nutritional support and insulin administration can be optimized to minimize secondary injury after subarachnoid hemorrhage." (PMID 22277085, 2012).
tetanus (4 papers, 2008 to 2022). A serious infectious disorder that follows wound contamination by the Gram-positive bacterium Clostridium tetani. "Although Arthus reactions have been studied extensively in animals and have been reported to occur only rarely after immunization, these reactions have been reported to occur after skin testing with tetanus toxoid and after the administration of insulin." (PMID 36248783, 2022). "All facilities in this study lacked the necessary equipment and medicines to provide this care, such as plaster of Paris, tetanus prophylaxis, and insulin." (PMID 30501022, 2018). "In addition, we can analyze the differences in surface marker expression of insulin, tetanus, and non-binding B cells by heat mapping." (PMID 34295938, 2021).
tetraplegia (4 papers, 2018 to 2025). "Further, women with tetraplegia had a lower insulin sensitivity index compared to controls without SCI, even after adjusting for visceral fat and total body lean mass." (PMID 35887592, 2022). "This is supported by the observation that 25 min of daily “moderate intensity” exercise reduced body mass index, percent body fat, and insulin resistance in participants with para-, but not tetraplegia, when compared to inactive groups with SCI." (PMID 30283348, 2018).
type 2 diabetic nephropathy (4 papers, 2016 to 2025). "The Rikenellaceae RC9 gut group has been negatively correlated with serum lipid, glucose, and insulin concentration but positively correlated with the cecal acetic acid and isobutyric acid levels in mice with type 2 diabetic nephropathy." (PMID 35334950, 2022). "Moreover, in the PT of human subjects with type 2 diabetic nephropathy, insulin significantly stimulated NBCe1 activity." (PMID 27247938, 2016).
uterine cancer (4 papers, 2021 to 2025). Primary or metastatic malignant neoplasm involving the uterine corpus and/or the cervix. "Therefore, the insulin and insulin-like growth factor axis and adipokines are always regarded to be the most studied candidates, although mechanisms that link high BMI and risk of ovarian and uterine cancers are not fully understood." (PMID 36313685, 2022).
Wolcott-Rallison syndrome (4 papers, 2014 to 2024). Wolcott-Rallison syndrome (WRS) is a very rare genetic disease, characterized by permanent neonatal diabetes mellitus (PNDM) with multiple epiphyseal dysplasia and other clinical manifestations, including recurrent episodes of acute liver failure. "Wolcott-Rallison syndrome in humans is characterized by infantile diabetes with defects in insulin secretion and folding." (PMID 38744890, 2024). "The follow-up for 18 months after diagnosis is detailed, illustrating both the therapeutic success of subcutaneous insulin therapy and the ongoing complications that patients with Wolcott-Rallison syndrome are subject to." (PMID 37873802, 2023). "Interestingly, this gene encompasses functions of bone mineralization, chondrocyte development insulin secretion and fat cell differentiation and has being related with the Wolcott-Rallison syndrome in humans." (PMID 25030608, 2014).
ZIKV infection (4 papers, 2022 to 2025). "To understand whether insulin signaling modulates survival to ZIKV infection in Drosophila, we injected flies carrying loss-of-function mutations in foxo and chico with MR766 and estimated survival rates over time." (PMID 35844546, 2022). "Our results present evidence of severe reduction in insulin gene expression in both Dicer-2 female and male mutants, therefore revealing insulin signaling as a target involved in the regulation of ZIKV infection." (PMID 35844546, 2022). "Collectively, this indicates a significant correlation between the RNAi and insulin pathways in Drosophila in the context of ZIKV infection." (PMID 35844546, 2022). "This indicates that insulin potentiates RNAi signaling in Drosophila and renders resistance to ZIKV infection differently in both sexes." (PMID 35844546, 2022). "Overall, these results indicate a strong link between RNAi and insulin signaling, through which Drosophila hosts can combat ZIKV infection." (PMID 35844546, 2022). "We show that ZIKV infection significantly reduces insulin gene expression in Dicer-2 mutants, suggesting an insulin antiviral role against ZIKV and a direct connection to RNAi immunity." (PMID 35844546, 2022). "To determine the correlation between the RNAi and insulin pathways during ZIKV infection, we used gene-specific primers to estimate Dicer-2 and Ago-2 expression in insulin mutants." (PMID 35844546, 2022). "Overall, this work identifies host carbohydrate metabolism and insulin signaling as components of Drosophila immunity against ZIKV infection and demonstrates that insulin works cooperatively with the RNAi antiviral immune pathway for host protection." (PMID 35844546, 2022). "Downregulated fructose-6-phosphate suggests that ZIKV infection may affect pathogenesis by interfering with the insulin-resistance pathway." (PMID 35693845, 2022). "To test whether insulin signaling confers RNAi resistance to ZIKV infection in Drosophila hosts, we estimated the transcript levels of Dicer-2 and Ago-2 in foxo and chico null mutants." (PMID 35844546, 2022). "We also find that insulin signaling, one of the main metabolic pathways involved in host-pathogen interactions, is targeted by ZIKV in Dicer-2 mutants, therefore reporting an antiviral role for insulin during ZIKV infection and a direct correlation to the RNAi pathway." (PMID 35844546, 2022). "Thus, we asked whether ZIKV infection affects insulin gene expression in Dicer-2 mutants and YW adult flies." (PMID 35844546, 2022). "Most importantly, the similarities of growth defects caused by chico mutations in Drosophila and insulin/IGF1 signaling pathway in vertebrates suggest that this pathway, chico in particular, plays a conserved role in antiviral immunity and metabolism during ZIKV infection." (PMID 35844546, 2022). "Insulin-mediated PI3K/AKT signaling also regulates the expression of RNAi genes Dicer2 and Argonaute2 via FoxO during West Nile and Zika virus infection." (PMID 40366172, 2025).
Acute Appendicitis (3 papers, 2021 to 2022). "Refined and unrefined carbohydrates have different glycemic indices, temporal effects on insulin release, nutritional elements (e.g., more fiber, protein and minerals in unrefined), and health effects (e.g., appendicitis and constipation with refined)." (PMID 35252289, 2022). "In this patient, a starvation state with continued insulin use in the setting of acute appendicitis led to her condition." (PMID 34437030, 2021).
Adrenal Hyperandrogenism (3 papers, 2014 to 2025). Excessive secretion of the androgen hormones dehydroepiandrosterone (DHEA), DHEA sulfate, and androstenedione, from the adrenal gland. "The biguanide metformin (N, N-dimethyl biguanide) is a hypoglycemic drug that improves insulin sensitivity, decreases insulin levels, and corrects ovarian and functional adrenal hyperandrogenism in PCOS." (PMID 36176868, 2022). "Therefore, we used DHEAS as a marker of adrenal hyperandrogenism and performed a cross-sectional analysis in a PCOS population from Romania, focusing on the association between insulin and DHEAS levels." (PMID 40944006, 2025). "It has been suggested that PCOS women with IR will not develop adrenal hyperandrogenism and at the same time will have lower levels of androstenedione, suggesting insulin inhibition of the putative factor responsible for stimulating both adrenal and ovarian androgen production via CYP17." (PMID 25310562, 2014).
advanced heart failure (3 papers, 2020 to 2022). Patients with advanced heart failure have severe limitations, experiences symptoms even while at rest and are mostly bedbound patients. "Another study showed that advanced heart failure causes myocardial insulin resistance by decreasing myocardial ATP levels and GLUT-4 translocation." (PMID 31935874, 2020).
alcoholic cardiomyopathy (3 papers, 2010 to 2023). A dilated cardiomyopathy which is associated with consumption of large amounts of alcohol over a period of years. "Chronic alcohol intake is associated with an increased risk of alcoholic cardiomyopathy, which may present with pathological changes such as myocardial insulin resistance, leading to ventricular dilation and cardiac dysfunction." (PMID 33868799, 2021). "Insulin sensitivity plays an essential role in myocardial pathology including ischemia and reperfusion injury, diabetic and alcoholic cardiomyopathy." (PMID 20585647, 2010).
alcoholic cirrhosis (3 papers, 2022 to 2024). "In another trial, silymarin was used for the long‐term treatment of patients with alcoholic cirrhosis, insulin‐treated diabetes, lipoperoxidation, and insulin resistance." (PMID 38726410, 2024). "Studies have demonstrated that AGIs are safe and effective in alcoholic cirrhosis, non-alcoholic cirrhosis, and patients with cirrhosis receiving insulin injections." (PMID 36618937, 2022).
alopecia areata (3 papers, 2021 to 2024). Loss of scalp and body hair involving microscopically inflammatory patchy areas. "Further studies are needed to evaluate the role of insulin as a prognostic factor in alopecia areata." (PMID 35639706, 2022). "Thus, it remains unclear if insulin is associated with higher risk of alopecia areata relapses." (PMID 35639706, 2022). "In spite of having similar fasting blood glucose levels, patients with alopecia areata had higher serum levels of insulin, c-peptide and HOMA-IR in comparison with healthy controls (p<0.05)." (PMID 35639706, 2022). "The results of the present study suggest that lipocalin-2 and insulin may serve as biomarkers in alopecia areata." (PMID 35639706, 2022). "In conclusion, lipocalin-2 and insulin may serve as biomarkers for alopecia areata." (PMID 35639706, 2022). "Increased levels of insulin, c-peptide, and HOMA-IR were observed in patients with alopecia areata in comparison with the control group (p<0.05)." (PMID 35639706, 2022). "The present analysis showed a positive correlation of insulin and HOMA-IR with the number of alopecia areata episodes." (PMID 35639706, 2022).
aortic aneurysm (3 papers, 2012 to 2026). A ruptured aneurysm located in the wall of the proximal portion of the descending aorta proceeding from the arch of the aorta. "Emerging evidence suggests multiple pathophysiological mechanisms through which insulin resistance, as reflected by an elevated TyG index, may contribute to aortic wall degeneration and the development of aortic aneurysm and dissection." (PMID 41499559, 2026).
aromatase deficiency (3 papers, 2015 to 2020). Aromatase deficiency disrupts the synthesis of estradiol, resulting in hirsutism of mothers during gestation of an affected child; pseudohermaphroditism and virilization in women; and tall stature, osteoporosis and obesity in men. "In aromatase deficiency, oestrogen replacement treatment regulates gonadotropin secretion, glucose metabolism and liver functions while reducing lipid and insulin levels." (PMID 30968679, 2020). "In humans, men with congenital aromatase deficiency are insulin resistant, and estrogen replacement therapy has been successfully used to improve insulin sensitivity in these men." (PMID 26491443, 2015).
asthenozoospermia (3 papers, 2015 to 2020). "Administration of vitamin D is recommended in the case of considerable deficiency, particularly in obese, insulin resistant women with low AMH levels, as well as in men with oligo- and asthenozoospermia." (PMID 26035242, 2015). "In addition, a pharmacological response to MYO was reported in insulin resistant patients with asthenozoospermia and low MMP (so-called asthenozoospermia associated with a metabolic factor)." (PMID 32392776, 2020).
atrioventricular block (3 papers, 2018 to 2022). A heart block that is initiated in the atrioventricular node. "Isoproterenol is known to cause insulin resistance and is often used to treat bradyarrhythmias from atrioventricular block." (PMID 30647979, 2018).
babesiosis (3 papers, 2012 to 2025). Babesiosis refers to a condition caused by microscopic parasites that infect the red blood cells. "However, increased cortisol and insulin levels were detected in dogs with babesiosis, with hypercholesteremia to be expected." (PMID 41437958, 2025). "Consequently, reduced-level of insulin during babesiosis seems other reason for less observed elevation in cholesterol and triglycerides content." (PMID 25653743, 2012).
bacterial pneumonia (3 papers, 2022 to 2025). Acute infection of the lung parenchyma caused by bacteria (e.g., Streptococcus pneumoniae, Haemophilus influenzae, Chlamydia pneumoniae, Mycoplasma pneumoniae, and Legionella pneumophila). "This study also found that insulin may increase the risk of bacterial pneumonia in people with T2D and COPD." (PMID 37242426, 2023). "Longer cumulative insulin use had association with increased risk of hospitalization for COPD, bacterial pneumonia, and invasive mechanical ventilation than insulin no-use." (PMID 37242426, 2023). "The cumulative incidence of hospitalization for COPD (Log-rank test p-value < 0.001), bacterial pneumonia (Log-rank test p-value < 0.001), and IMV (Log-rank test p-value < 0.001) were significantly higher in insulin users than in non-users." (PMID 37242426, 2023).
Brugada syndrome (3 papers, 2014 to 2025). A genetically heterogeneous condition characterized by complete or incomplete right bundle branch block accompanied by ST elevation in leads V1-V3. "Malignant ventricular arrhythmia due to Brugada syndrome has been postulated as a cause, since a glucose-insulin bolus can unmask the Brugada electrocardiographic signature in genetically predisposed individuals." (PMID 24715918, 2014).
calcification (3 papers, 2011 to 2023). Process by which organic tissue becomes hardened by the physiologic deposit of calcium salts. "In parallel, LAD showed greater affectation in calcifications for the case of mIR without insulin." (PMID 36834662, 2023). "For instance, mIR patients without insulin treatment that had an intake of vitamin D or calcium usage helpers did not develop calcifications (two individuals), whilst two mIR subjects without insulin input but with calcium supplements did show accumulated plaque." (PMID 36834662, 2023).
carnitine deficiency (3 papers, 2014 to 2024). "Some studies have shown that carnitine deficiency leads to impaired insulin sensitivity and high blood glucose." (PMID 39085907, 2024). "Although urinary loss of FC was prevented with insulin, further studies using isolated cell systems are warranted to determine whether insulin directly regulates the expression of OCTN2, thus preventing carnitine deficiency from renal routes." (PMID 34833964, 2021).
carpal tunnel syndrome (3 papers, 2024). Entrapment of the median nerve in the wrist that is characterized by numbness, tingling and painful movement. "Although hyaluronic acid, hyalase, 17-alpha-hydroxyprogesterone, insulin, and ozone theoretically hold promise in alleviating the symptoms of carpal tunnel syndrome, their actual efficacy could not be fully assessed in this analysis due to the limited number of included studies." (PMID 38753671, 2024).
central precocious puberty (3 papers, 2017 to 2021). "Third, the most probable connection between adrenal and gonadal maturation is insulin–IGF-1 axis, as increased concentrations of IGF-1 and insulin have been associated with both PA and central precocious puberty." (PMID 29163361, 2017). "Since members of the IGF family are involved in the onset of puberty, we aimed to identify polymorphisms in insulin (INS), IGF-1, IGF-2, IGF-1 receptor (IGF1R), IGR2R, and IGF binding protein 3 (IGFBP-3) that may alter the risk for development of central precocious puberty." (PMID 30249230, 2018).
Cerebral atrophy (3 papers, 2021 to 2024). Atrophy (wasting, decrease in size of cells or tissue) affecting the cerebrum. "Cerebral atrophy caused by uncontrolled glycemia and the consequent reduction in neural and glial cells tend to be stabilized by glycemic control, as insulin plays an important role in maintaining cognitive performance." (PMID 38775400, 2024).
cervical adenocarcinoma (3 papers, 2015 to 2019). An adenocarcinoma arising from the cervical epithelium. "We then tested whether insulin-promoted TCTP phosphorylation occurs also in cells other than 293T cells, such as human cervical adenocarcinoma HeLa cells." (PMID 25854427, 2015).
Chorea (3 papers, 2014 to 2026). Chorea (Greek for 'dance') refers to widespread arrhythmic involuntary movements of a forcible, jerky and restless fashion. "The patient was started on insulin and clonazepam and the chorea resolved after proper control of the glucose level." (PMID 24716012, 2014). "The patient was managed with insulin therapy, and chorea subsided within 48 hours." (PMID 41503046, 2026). "Therefore, the significantly shorter recovery time of the insulin-treatment-only group than that of the additional anti-chorea medication group may reflect a less severe disease in the former compared with that in the latter." (PMID 32005905, 2020).
chronic kidney failure (3 papers, 2017 to 2020). "Other standard reasons for referral were significant comorbidities (cardiovascular disease, chronic kidney failure) or requiring insulin." (PMID 28330453, 2017).
colon adenocarcinoma (3 papers, 2010 to 2021). "Similarly, a ketogenic diet (80% medium chain triglycerides) fed to mice with implanted colon adenocarcinomas reduced tumor weight, while the inclusion of hydroxybutyrate in drinking water counteracted the stimulation of tumor growth by insulin infusion." (PMID 20148110, 2010). "Our first question aimed to test cellular effects on the human colon adenocarcinoma cell line SW480, induced by the anti-anabolic (orlistat, lonidamine and DON) and anti-catabolic (GH, insulin and indomethacin) compounds, either alone or in combination." (PMID 33664364, 2021).
colorectal polyps (3 papers, 2020 to 2023). "Though the underlying mechanism of the association between NAFLD and colorectal polyps is still unclear, the significant roles of insulin resistance, inflammatory response and obesity in the pathophysiological pathways of NAFLD and colorectal polyps have been suggested." (PMID 37240431, 2023).